VEGFA (vascular endothelial growth factor A)
Diseases named in the same sentence as VEGFA in open-access papers (continued):
Sharing a sentence is not in itself a finding about the gene and the disease.
tumor (continued). "CAF is an abundant source of VEGFA and other pro-angiogenetic factors such as platelet-derived growth factor C (PDGFC), fibroblast growth factor 2 (FGF-2), and C-X-C motif chemokine 12 (CXCL12/SDF-1), which directly or indirectly regulates tumor neovascularization." (PMID 35327514, 2022). "Furthermore, Xing M demonstrated that activation of MAPK signaling pathway resulted in upregulation of tumor-promoting genes (e.g. VEGFA, MET, HIF1A, UPA, UPAR, TGFB1, and TSP1) as well as downregulation of tumor suppression and thyroid genes (e.g. TIMP3, SLC5A8, DAPK1, NIS, TSHR, and TPO)." (PMID 35600399, 2022). "Consistent with this phenomenon, we found that VEGFA was highly expressed in malignant/HPC-like cells, while PLVAP+ ECs notably expressed its receptor KDR (VEGFR2), suggesting that these cells may interact within the tumor microenvironment." (PMID 36238304, 2022). "Based on our research, we postulate that specifically upregulating LBH during NPC therapy might ameliorate tumor metastasis and angiogenesis, achieving better therapeutic efficacy for NPC patients via exosome-mediated VEGFA inhibition, and this is likely our next research topic." (PMID 34975330, 2022). "Several proteins that are involved in tumor vascularization were detected: histidine-rich glycoprotein (HRG), α-2-HS-glycoprotein, leucine-rich α-2-glycoprotein (LRG), secreted GRP78, macrophage migration inhibitory factor (MIF), VEGFA, and hepatoma-derived growth factor." (PMID 35659255, 2022). "Therefore, genes VEGFA, ANXA1, HSP90B1, PSMA7, PRDX6, and PPP1CB may be new targets for anti-tumor effects in the future." (PMID 36741702, 2022). "Vascular endothelial growth factor-A (VEGF-A), -C, and -D released by cancer cells stimulate the growth of peripheral tumor lymphatic vessels and promote the invasion of cancer cells into nearby lymph nodes (known as sentinel lymph node, SLN) to enhance tumor metastasis." (PMID 36266717, 2022). "In May 2009, the US FDA granted accelerated approval to a monoclonal antibody against vascular endothelial growth factor A (VEGF)—an important molecule promoting endothelial cell proliferation, new vessel formation, and subsequent rapid tumor growth in recurrent GBM patients." (PMID 35625738, 2022). "In contrast to C4-Mye enriched in blood, C6-Mye preferred tumor and paratumor tissue and highly expressed 591 genes, including the M2 macrophage marker gene MCR1 (CD206), and highly expressed the M2 macrophage-related protumorigenic genes TGF-β, IL10, VEGFA and MMP9." (PMID 35562760, 2022). "Additionally, the overexpression of HMGA2 in leiomyomas was shown to be associated with increased vasculature density, demonstrated by the increased expression of angiogenic factors and receptors, such as VEGFA, EGF, bFGF, TGFα, VEGFR1, and VEGFR2, which likely contribute to tumour growth." (PMID 35805007, 2022). "miR-205 functions as tumor suppressor miRNA and improves the response to the TK inhibitors gefitinib (GEF) and LAP and to TRA through abrogating the expression of HER3 along with vascular endothelial growth factor A (VEGF-A) and targets AKT-mediated pathway in BC cells." (PMID 34524579, 2022). "Using antibody–drug conjugates to ablate CD276 + glioma cells simultaneously impaired tumor vescular, indicating a novel insight on the combination of anti-CD276 with anti-angiogenesis, which was supported when CD276 was confirmed to positively be related with VEGFA and MMP2." (PMID 35135556, 2022). "In addition, we found that these ligands secreted by hypoxia-related GBM cell types, namely, MES1-like tumor cells, MES2-like tumor cells, and TAM-1, may stimulate angiogenesis via, for example, ADM, ANGPTL4, GDF15, and VEGFA." (PMID 35669791, 2022). "In addition to tumor tissues, we also subjected Moc2 EphB4 KO and control cell lines to RNA-seq analysis and observed similar changes in the genes involved in the VEGF signaling pathway including VEGFA, DLL1, NRP2." (PMID 35725568, 2022).
tumor (continued). "Indeed, a very frequent mutation of the tumour suppressor gene VHL in ccRCC (>80% of cases) dysregulates hypoxia-inducing factor (HIF) inducing overexpression of vascular endothelial growth factor A (VEGF-A) and platelet-derived growth factor (PDGF) leading to tumour growth." (PMID 36551652, 2022). "Based on these findings, we speculated that tumor bud-derived CCL5 increased the number of α-SMAhigh CD90high FAPlow fibroblasts and promoted tumor angiogenesis via the increase in VEGFA and the transdifferentiation of fibroblasts into vascular endothelial cells." (PMID 35241150, 2022). "Importantly, dynamic contrast enhanced MRI analyses have indicated that Hypoxia Inducible Factor 1 (HIF-1) (hypoxia marker) and Vascular Endothelial Growth Factor A (VEGFA) staining and tumor vascularity significantly correlate with worse progression-free and overall GB patient survival." (PMID 33535436, 2021). "Its activity is due to the ability to bind the human vascular endothelial growth factor A (VEGF-A) inhibiting its interaction with VEGF receptor tyrosine kinases and blocking the angiogenesis, and the growth of new vessels from pre-existing vasculature, which is a critical step in tumor progression." (PMID 33921167, 2021). "Tumor tissue microarrays were stained for hypoxia-inducible factor-1α (HIF1A), solute carrier family 2 member 1 (SLC2A1, also known as glucose transporter 1 (GLUT1)), carbonic anhydrase 9 (CA9), and vascular endothelial growth factor A (VEGFA) and classified into low- or high-expression groups." (PMID 33810575, 2021). "Hypoxic tumor cells around dying tumor cells in the TC can also produce various kinds of cytokines regulated by HIF, such as C–C chemokine ligand type 5 (CCL5), CXCL12, vascular endothelial growth factor A (VEGF-A), endothelin (ET)-1, ET-2 and semaphorin-3A (Sema3A)." (PMID 34172088, 2021). "The obese tumor microenvironment favors the recruitment of macrophage and the activation of NLRC4 inflammasomes in these cells promotes the production of adipocyte-originated growth factor vascular endothelial growth factor-A (VEGF-A), thereby promoting angiogenesis." (PMID 34276697, 2021). "In addition, the antiangiogenic activity of fucoidan was confirmed in MDA-MB-231 cells through the reduction of VEGFA, IGF-I, MMP-2, and MMP-9 levels, basic fibroblast growth factor (bFGF), and the blockade of the adhesion and extravasation of tumor tissue to vascular endothelial cells." (PMID 34200897, 2021). "Additionally, a high level of VEGFA was relevant to hypoxia, angiogenesis, and immune suppression of the tumor microenvironment (TME), which elaborated the mechanism of tumors' innate resistance to ICIs and uncovered that upregulated VEGFA enhanced the malignancy of tumor cells." (PMID 34497663, 2021). "On the one hand, tumor-associated neutrophils (TANs) may contribute to local hypoxia via respiratory burst-dependent oxygen expenditure; on the other hand, HIF1 regulates neutrophil functions and may promote neutrophil expression of pro-tumor factors, such as TNF-alpha, VEGFA, and MMP9." (PMID 33810575, 2021). "Importantly, similar to short-term Olaparib treatment, RT-PCR analysis of parental and Olaparib-resistant A2780, OVCAR8, and PEO1 cells showed mRNA upregulation of several essential tumor-promoting genes, such as MMP9, VEGFA, CCND1, and BCL2L1, which are known STAT3 target genes." (PMID 34956861, 2021). "Furthermore, a high level of VEGFA in HCC cells could lead to excessive production of hepatocyte growth factor (HGF), which induces tumor cell proliferation." (PMID 34680462, 2021). "Therefore, given that both the VEGFA and APLN exerted angioplasty effects on the stroma in a paracrine way, the hypoxia-related signaling initiated by the aberrantly accumulated HIF1 in the KIRC tumor can be acknowledged as their shared upstream origin." (PMID 35079698, 2021).
tumor (continued). "It directly targets the vascular endothelial growth factor A (VEGF-A) inhibiting the interaction with VEGF tyrosine kinase receptor, which is overexpressed on the surface of endothelial cells as a result of tissue hypoxia, and interrupts aberrant tumor angiogenesis." (PMID 33803885, 2021). "On the other hand, in our study we observed that the expression of upstream signaling molecules such as VEGFA and FGF1 was also regulated by KDM6B, which may form a positive feedback loop, strengthening the inhibition of tumor progression after targeted blockade of KDM6B." (PMID 33664867, 2021). "In addition, we found that SALL4 could exert its tumor-promoting effect via modulating Akt/GSK-3β axis and VEGFA expression." (PMID 32513235, 2020). "Additionally, both VEGFA and ANGPT2 protein levels were significantly associated with the tumor size and lymph node metastasis only in ADC, not SQC." (PMID 31892982, 2020). "HIF-2α transcriptional targets EDN1, EPO, GNA14, and VEGFA were significantly upregulated in the tumor bed but not the surrounding liver tissue, indicating hyperactivation of the hypoxia signaling pathway within the tumor." (PMID 32235007, 2020). "Also, clinical studies have shown a significant negative correlation between VEGFA expression and tumor prognosis." (PMID 33362712, 2020). "We hypothesise that bevacizumab-800CW could accumulate at the mucosal side because the tumour microenvironment was not yet normalised after nCRT, with still increased levels of VEGFA." (PMID 31533965, 2020). "Although our study focuses on Cox-2/PGE2 as the downstream effector of caspase-3, radiation-induced dying NSCLC cells may also secrete additional growth-stimulating factors, such as vascular endothelial growth factor A (VEGF-A), to contribute to tumor relapse after radiotherapy." (PMID 33180744, 2020). "Preclinical studies linked this effect to the upregulation of HLA molecule expression in tumor cells, favoring increased antigen presentation and activation of antitumor T cells, together with the downregulation of certain immunosuppressive factors such as PD-L1, IL1, IL8, NT5E, and VEGFA." (PMID 31730502, 2019). "Moreover, Akirin2 levels were positively correlated with VEGFA expression in CCA tissues, indicating that Akirin2 might promote tumor angiogenesis in human CCA." (PMID 30886152, 2019). "Recent evidence indicates that tumor-derived vascular endothelial growth factor A (VEGF-A) and prostaglandin E2 (PGE2) cooperatively induce FasL expression in endothelial cells, which leads to excessive turnover of CD8 + T cells and reduce anti-tumor immune responses." (PMID 31500650, 2019). "In hypoxic environments, as in tumor tissues, hypoxia-inducible factor 1α (HIF-1α) is commonly induced, which activates both LDH-A, which is one of the LDH isozymes, and pro-angiogenesis factors such as vascular endothelial growth factor (VEGFA, VEGFR) via the same molecular pathway." (PMID 30298469, 2019). "However, no quantitative analysis exploring tumor-specific alterations of VEGFA isoforms expression in HCC has been reported yet." (PMID 29888133, 2018). "It is possible that psammaplins stall tumor progression by inducing the expression of proliferation inhibiting and cell death promoting genes, without stimulating the expression of survival genes (i.e., VEGFA)." (PMID 30423844, 2018). "Bevacizumab binds to vascular endothelial growth factor A (VEGF-A) and prevents the binding of VEGF-A to VEGF receptors on the surface of endothelial cells, inhibiting endothelial cell proliferation and new blood vessel formation, thereby leading to normalization of the tumor vasculature." (PMID 29553864, 2018). "In fact, a recent study demonstrated that VEGFA produced in the tumor microenvironment directly increases PD-1 expression on intratumoral CD8+ T-cells and combined anti-PD-1 and anti-VEGFA blockade showed a synergistic effect in tumors with high levels of VEGFA." (PMID 28403223, 2017).
tumor (continued). "One week sunitinib treatment also resulted in increased mRNA expression levels of VEGFA, CD31 (an endothelial cell marker), Oct4 and Snail compared to the control treatment group, supporting that short term sunitinib treatment induces greater hypoxia in the tumor tissue." (PMID 29383148, 2017). "Secondly, the regulation mechanisms of VEGFA in the tumor stem-like cells is not clear." (PMID 28163656, 2017). "The results showed that the expression levels of vascular endothelial growth factor A (VEGFA), angiopoietin-2 (ANGPT2), and tissue plasminogen activator (PLAT) were suppressed in ADAM9-silenced cells, which in turn leads to decreases in angiogenesis, vascular remodeling, and tumor growth in vivo." (PMID 29118335, 2017). "The study revealed that the metastatic propensity was determined by the tumor microvascular density rather than the fraction of hypoxic tissue, and vascular endothelial growth factor-A and interleukin-8 were identified as important drivers of tumor angiogenesis." (PMID 29017512, 2017). "In an aortic ring assay anti-VEGFA treatment abrogated microvessel sprouting in one cell line but not in the other, and tumor recurrences following anti-VEGFA treatment could be divided in distinct resistance phenotypes." (PMID 27633774, 2017). "In addition, mixed phenotypes of TAMs that co-express proinflammatory genes such as TNF and IL-1 together with known tumor-promoting genes including VEGFA and MMP9 have been observed in various tumor models including renal cell carcinoma and mammary adenocarcinoma." (PMID 27487154, 2016). "Immunoblotting of lysates from individual tumours showed that the pY1173/VEGFR2 ratio was significantly higher at D12 in tumours from WT mice compared with Vegfr2Y949F/Y949F mice (lower part shows representative immunoblot), correlating with the VEGFA signalling data from lung lysates." (PMID 27005951, 2016). "The fact that germline variant frequencies were not retained in matched FFPE samples may be related to somatic changes in tumor DNA and not to technical errors, as exemplified in the E2F3 and VEGFA germline variants that were validated with Sanger sequencing." (PMID 26039550, 2015). "In agreement with findings that ROS may regulate angiogenesis and tumor growth through HIF-1α and VEGF, over-expression of Nrf2 in tMSC led to a diminished hypoxic response through destabilization of HIF-1α and reduced VEGFA and ADM expression." (PMID 24491031, 2014). "Recent studies have shown that vascular endothelial growth factor A (VEGF-A) signaling through vascular endothelial growth factor receptor-2 (VEGFR-2) is involved in MDSCs precursors recruitment to metastases and, once within the tumor, MDSCs can further mature into tumor-promoting macrophages." (PMID 25136356, 2014). "In other words, the gradient of NRP-1 and VEGFR-2 expression between the tumor and peritumoral tissue may attract VEGFA into the peritumoral tissue, where it combines with peritumoral NRP-1 and VEGFR-2 in hepatocytes, which may decrease tumor endothelial cell proliferation." (PMID 25333267, 2014). "Furthermore, genes previously associated with ccRCC susceptibility or carcinogenesis, apolipoprotein C-I (APOC1), vascular endothelial growth factor A (VEGFA), scavenger receptor class B, member 1 (SCARB1) were found to be highly overexpressed in tumour tissue in both analysis." (PMID 23526956, 2013). "During hypoxia of tumor cells, the upregulated hypoxia inducing factor (HIF)-1α forms a heterodimer with HIF-1β to become a transcription factor HIF-1 that activates pro-angiogenic genes such as vascular endothelial growth factor A (VEGFA), to promote angiogenesis for tumor growth and metastasis." (PMID 24013378, 2013). "This lack of correlation may be due to their roles in different steps of tumorigenesis, e.g., VEGFA overexpression supports early vascularisation under hypoxic conditions, whereas OPN is involved in advanced processes, such as tumor growth in deregulating the extracellular matrix." (PMID 22895562, 2012).
tumor (continued). "Our results seem to indicate that combining information from genotyping of rs699947 (VEGFA, AC), rs2269772 (ITGA, AA) and tumour histology could allow clinicians to individuate gastric cancer at high risk for recurrence either with peritoneal or hematogenous metastases." (PMID 22808003, 2012). "Through the production of VEGFA, TGFβ, and tumor necrosis factor-α (TNFα), tumor cells enhance the expression of the chemoattractants S100A8 and S100A9 in lung endothelium and myeloid cells, which in turn promote tumor cell homing and adhesion to the metastatic site." (PMID 22482059, 2012). "Through theproduction of vascular endothelial growth factor A (VEGFA), they contribute to angiogenesis;by producing components of ECM, such as collagens and ECM degrading enzymes, such as MMPs,they contribute to stromal remodeling and to cell migration within the tumor." (PMID 22969725, 2012). "The immunoreactivity of VEGFA, bFGF, TGF-β, MCP-1, TSP-1, TIMP-1, TIMP-2, and endostatin was observed mainly in the tumor and non-tumor hepatic cells, showing a predominant cytoplasmic staining, with the positive liver cells distributed in both the tumor tissue and surrounding liver." (PMID 21152281, 2010). "Serum vascular endothelial growth factor-A is therefore not all tumour-derived." (PMID 12454774, 2002). "In the BIOSTORM study, neither p-ERK, p-VEGFR2, nor VEGFA copy number status was significantly correlated with recurrence prevention by sorafenib, suggesting that the mechanisms of action of the drug and tumor biology in response to therapy are more complex than previously understood." (PMID 40593458, 2025). "In addition, significant interaction strength via VEGFA-mediated signaling was observed between these PTC subsets and arterial endothelial, pericyte, and fibroblast populations, pointing to their potential roles in modulating angiogenesis and stromal remodeling within the tumor ecosystem." (PMID 41357133, 2025). "Therefore, we performed immunohistochemical analyses on tumor tissues from three NSCLC patients with osimertinib resistance to analyze alterations in the expression levels of EMT markers and vascular endothelial growth factor A (VEGFA) before and after the development of osimertinib resistance." (PMID 39375945, 2024). "Our results may also offer an explanation for why anti-angiogenesis therapy (anti-VEGFA; bevacizumab) generates clinical benefit in the treatment of metastatic colon cancer but not when added to adjuvant chemotherapy following primary tumor resection." (PMID 38473429, 2024). "In addition, excessive expression of VEGFA inhibits T cells cytotoxicity in HCC microenvironment resulting in tumor immunosuppression, while sorafenib could not reverse this." (PMID 36906615, 2023). "Furthermore, we found that DOKD inhibited CT26+ tumor cell growth by regulating inflammation, metastasis, and angiogenesis by activating the IL-17/TLR4/NF-κB p65 pathway and inhibiting the activation of the Src/HIF-1α/Erk1/2/Snail/N-cadherin/Vimentin/MMP9 and Erk1/2/HIF-1α/STAT3/VEGFA pathways." (PMID 37239383, 2023). "To distinguish whether FAM114A1 upregulation is a hypoxia related or predominantly related to VEGFA activation, we explored into conditions involving non-hypoxia related VEGFA activation such as in cell growth, apoptosis, cell proliferation and tumor development." (PMID 36006949, 2022). "Importantly, S100A4(+)/HIF-1α(−) tumor cells were recruited along the surface of host preexisting vessels in vascular-rich areas of non-Ps perinecrotic lesions, whereas high VEGFA mRNA expression was found in S100A4(+)/HIF-1α(+) GBM cells in the adjacent areas." (PMID 35392912, 2022). "Furthermore, the functions of the CXC chemokine-VEGFA network in patients with COAD were mainly related to chemokine activity, cytokine activity, and growth factor activity, as demonstrated by GO enrichment analysis, all of which are closely related to tumor angiogenesis." (PMID 36246978, 2022).